CD44 (CD44 molecule (IN blood group))
Diseases named in the same sentence as CD44 in open-access papers (continued):
Sharing a sentence is not in itself a finding about the gene and the disease.
cancer (continued). "Yu’s study showed that miR-106b was overexpressed in CD44(+) GC stem-like cells and could retain cancer stem cell characteristics through modulating TGF-β/Smad signaling pathway." (PMID 31637133, 2019). "CD44 is a widely used marker for cancer stem cells in solid tumors including HCC." (PMID 31819089, 2019). "CD44+/CD24- cancer cells were assessed under sulconazole treatment." (PMID 31480284, 2019). "Previous studies have utilized HA for targeting CD44-overexpressing cancer cells." (PMID 31060303, 2019). "Ivermectin decreased the CD44+/CD24−-expressing cancer cell population from 14.2% to 1.6%." (PMID 31658701, 2019). "The role of CD44 and its isoforms in advanced cancer patients remains unclear as to which markers may be of value in determining prognosis." (PMID 30788285, 2019). "Furthermore, interaction with membrane-anchored proteins, like CD44, favors accumulation of HA-based nanocarriers in cancer cells, which makes anti-cancer therapy one of the most common applications of HA-based drug delivery systems." (PMID 31311150, 2019). "Compared to HA, oHA could inhibit the clustering of CD44 and then make the hybrid materials cell permeable for more efficient uptake by cancer cells." (PMID 31380195, 2019). "Therapies targeting CD44 show their efficiencies in prevention of cancer." (PMID 31049070, 2019). "LncRNA DGCR promoted cancer cell stem-like properties by targeting miR-330-5p/CD44 axis in NSCLC." (PMID 31300015, 2019). "Thus, we showed that Skp2 is important for maintaining the cancer stem-like phenotype of DU 145 mesenchymal cells in term of the CD44+CD24− phenotype." (PMID 30952903, 2019). "The CD44 isoform, CD44v6, was found expressed only in both cancer SW480 and SW620 cells." (PMID 31139149, 2019). "CD44 is a well-known gastric CSC marker which is also a CSC marker in various other cancers." (PMID 30696080, 2019). "First, we found that transient treatment of Doc for 2 days could increase levels of cancer stem cell markers including CD44, Nanog and Sox2 in both LNCaP cells and CWR22Rv1 cells." (PMID 30621625, 2019). "As the putative stemness biomarker, CD44 also functioned as a multifunctional cell surface adhesion receptor, and contributed to cell-cell and cell-matrix adhesion, cell migration, epithelial to mesenchymal transition and cancer metastasis." (PMID 31695791, 2019). "Interestingly, we found that cancer stem cell markers (CD44, Nanog, Sox2) were overexpressed in LNCaP DocR and CWR22Rv1 DocR cells compared to their parental cells." (PMID 30621625, 2019). "The present study extends knowledge of the role of CD44 in cancer cell biology." (PMID 30909497, 2019). "Along this line, CD44 is expressed by GBM cancer stem cells, which promotes aggressive GBM growth." (PMID 31466397, 2019). "Furthermore, this treatment reduced the sphere formation efficiency and the number of CD44+/CD24− cancer cells." (PMID 31253779, 2019). "In addition, CD44, downstream of circFNDC3B, has complex regulatory mechanisms in cancer development." (PMID 30963578, 2019). "Therefore, we present here the first systemic meta-analysis and TSA on the relationship of CD44 and its isoforms expression with clinical outcomes in patients with advanced cancer." (PMID 30788285, 2019). "The adhesion molecule CD44 is expressed in cancer stem-like cells (CSCs)." (PMID 29971631, 2019). "Cells undergoing EMT express biomarkers such as CD44, recognized as a cancer stem cell marker." (PMID 30754655, 2019). "CD44 is commonly used as a cell surface marker of cancer stem-like cells in epithelial tumors." (PMID 31921651, 2019). "Cancer stem cell biomarkers were characterized using immunocytochemistry for P63, CD44, and CK18." (PMID 30992079, 2019). "Moreover, CD15, CD44, CD166, and ALDH1A1 positivity were each independently associated with a shorter PFS, independently of higher N and cancer stage as well as other clinicopathological factors." (PMID 31428052, 2019).
cancer (continued). "The CD44 isoform CD44v-xCT regulates redox in cancer stem cells." (PMID 31480284, 2019). "Finally, we observed that CCL20 and IL-17A levels were both positively associated with levels of CD44 and MMP3, which are closely related to cancer progression." (PMID 31387598, 2019). "Therefore, it is of great importance to identify the functions of CD44 splicing isoforms, and to investigate the mechanisms of alternative splicing of CD44 in different cancers." (PMID 31857793, 2019). "CD44 expression can be correlated with markers of cancer stem cells." (PMID 31728117, 2019). "CD44, which can selectively bind to HA, has been identified by several studies to play crucial roles in cancer proliferation, invasion, and metastasis in various cancers." (PMID 31109321, 2019). "Moreover, RT-PCR analysis showed inhibition of the expressions of cancer stemness-associated BMI1 and CD44 genes, markers of stemness, when cancer cells were treated with BEP as compared to control." (PMID 30691094, 2019). "In this study, hyaluronic acid (HA), a natural polysaccharide that can specifically bind to CD44 receptors, was conjugated onto laponite® (LAP) nanodisks for the encapsulation and specific delivery of the anti-cancer drug doxorubicin (DOX) to CD44-overexpressed cancer cells." (PMID 30960121, 2019). "While the PC3 CD44+/CD49bhigh sub-populationrevealed cancer stem-like properties." (PMID 30825285, 2019). "P-gp and BCRP are known to interact with CD44 to modulate cancer cell migration/invasion." (PMID 31561453, 2019). "In addition, the predictive value of cancer stem cell related markers, like CD44, ALDH1 have been demonstrated for chemoresistance." (PMID 31519183, 2019). "CD44 exerts a multitude of biological functions, especially in cell adhesion and migration, and its deregulation has several pathological implications, including a putative role in cancer cell dissemination." (PMID 30474821, 2019). "In some previous reports, CD44 was detected in cancer cell-derived EV." (PMID 30909497, 2019). "In addition, miR-34a has also been found to participate in controlling cancer stemness, by targeting CD44." (PMID 31569404, 2019). "Finally, multivariate cox regression analysis demonstrates a significant reduction in cancer-specific survival over a 5-year term and that was associated with co-expression of PYK2 and the stem cell marker CD44." (PMID 31118051, 2019). "In this context, hyaluronic acid (HA) has gained increasing attention as targeting ligand due to its high affinity with CD44, a glycoprotein receptor overexpressed in many solid tumor cells (e.g. lung, breast, pancreatic, renal tumor), in metastasis, as well as in cancer stem cells." (PMID 30804375, 2019). "I believe that important information can be obtained from these studies on HA/CD44-activated miRNAs and lncRNA that may be very valuable for the future development of innovative therapeutic drugs for the treatment of matrix HA/CD44-mediated cancers." (PMID 31293964, 2019). "The GDH nanogel was preferentially accumulated in CD44-over-expressing A549 cancer cells." (PMID 31266194, 2019). "Future studies could examine rhPRG4’s anti-invasive effects in other types of cancer, in particular high CD44-expressing cancer cells in HA-rich stromal environment." (PMID 31361756, 2019). "Elevation of CD44 has been observed in some other drug-resistant cancer cell lines." (PMID 30935014, 2019). "Notably, DCA downregulated the expression of the cancer stem cells markers CD24/CD44/EPCAM only in PANC-1 but inhibited spheroid formation/viability in both cell lines." (PMID 31109089, 2019). "Numerous reports have indicated that CD44 is related to cancer stemness activity." (PMID 31109321, 2019). "Cancer stem cells, CD44+/CD90+ cells, yield elevated mEAK-7 and activated mTOR signaling." (PMID 31288154, 2019).
cancer (continued). "CD44 is a trans-membrane glycoprotein involved in several cellular processes, including migration and adhesion and is widely used as a surface marker to isolate cancer stem cells from solid tumours." (PMID 31382922, 2019). "CD44 is a type I transmembrane glycoprotein known to facilitate cell adhesion, spreading, migration, invasion, ROS defense, and drug resistance in a variety of cancer types." (PMID 31416894, 2019). "As our analysis of tumorspheres indicated that the fusion protein might actually help the expansion of cancer stem cells (CSCs), we further assessed this by flow cytometry using anti‐CD44 antibody." (PMID 30548174, 2019). "HA can regulate cancer cell proliferation and migration via CD44." (PMID 31057402, 2019). "CD44 is recognized as a typical CSC surface marker in various cancers." (PMID 31534498, 2019). "In addition, HA can interact with overexpressed receptors in cancer cells such as cluster determinant 44 (CD44) and receptor for HA-mediated motility (RHAMM) and be degraded by a family of enzymes called hyaluronidase (HAdase) to release drugs or molecules." (PMID 31262049, 2019). "It is well known that the alternative splicing of CD44 pre-mRNA is a main source of the diverse CD44 isoforms, and these isoforms with different properties might have diverse effects on cancer progression." (PMID 31857793, 2019). "CD44 is the best-characterized receptor for HA and is itself a marker for cancer stem cells." (PMID 31762938, 2019). "Despite numerous studies having investigated whether CD44, CD44v6, and CD44v9 may be potential prognostic indicators in many cancers, some findings are controversial." (PMID 30788285, 2019). "In various two- and three-dimensional (2D and 3D) culture models, CUR decreased the activity of cancer stem cells by inhibiting tumor cell proliferation, downregulating cancer stem-cell markers (i.e., CD44 and Oct4 [octamer-binding transcription factor 4]), and inducing apoptosis." (PMID 31013694, 2019). "Moreover, the Has2 enzyme is involved in hyaluronan (HA) synthesis and enhances the HA/CD44 cancer stemness pathway." (PMID 31109321, 2019). "Furthermore, we observed that Skp2 downregulation led to the decrease in subpopulation of CD44+CD24− cancer stem-like cells." (PMID 30952903, 2019). "The surface marker CD44 was investigated as a possible marker for cancer stem-like cells." (PMID 31921651, 2019). "This discrepancy may be explained by the differential pro-stemness roles of different CD44 isoforms in different types of cancers." (PMID 31108941, 2019). "CD44 is expressed in CAFs and enhances the interactions between cancer cells and CAFs which may suggest the contribution of CD44 in tumorigenicity, stemness and drug resistance." (PMID 31579438, 2019). "We observed that mesenchymal cells are enriched in a CD44+CD24− cancer stem cell subpopulation." (PMID 30952903, 2019). "The binding interaction between HA and CD44 isoforms often stimulates aberrant cellular signaling processes and appears to be responsible for the induction of multiple oncogenic events required for cancer-specific phenotypes and behaviors." (PMID 31293964, 2019). "In addition, siRNA‐mediated knockdown of NOTCH3 in HuH7 cells resulted in a decrease in spheroid formation, suggesting that NOTCH3 is an important mediator of CD44‐mediated maintenance of cancer stemness in HuH7 cells." (PMID 30636370, 2019). "Inhibition of Ezh2 could reverse Doc-induced expression of Nanog, Sox2, CD44 and Doc-induced enriched population of cancer stem cells." (PMID 30621625, 2019). "Interestingly, in both models, the expressions of various cancer stem cells (CD44, CD90, CD133, and EpCAM) were also decreased." (PMID 30858465, 2019). "CD44 has been described as a marker of CSC in some carcinomas." (PMID 30999901, 2019).
cancer (continued). "The binding affinity of this conjugate to CD44 antigen was improved by multivalent binding of Apt-Lip, compared to that of the aptamer alone; consequently, Apt-Lip delivered more Dox to the target CD44+ cancer cells." (PMID 29617327, 2018). "In addition, this review demonstrates nanodelivery systems using HA for encapsulating and targeting active molecules, as well as alternative approaches for targeting CD44 in cancer therapy." (PMID 30961058, 2018). "Therefore, CD44 is a common stem cell biomarker, and a marker for cancer stem cells (CSCs), which are otherwise known as cancer initiating cells." (PMID 30544868, 2018). "Also, the gene silencing effect of the green fluorescent protein gene using these nanocomplexes is demonstrated in CD44 overexpressing cancer cells." (PMID 29899207, 2018). "In addition to DNA methylation, histone modifications are involved in the epigenetic regulation of the cancer surface markers CD44 or CD133." (PMID 29721188, 2018). "CD44, previously known as an adhesion molecule, is expressed in CSCs of various types of cancers." (PMID 29785244, 2018). "This could be due to repeated circulation and prevention of RES uptake, which enables nanoparticle to be taken up by cancer cells owing to overexpression of CD44." (PMID 29534519, 2018). "We demonstrated that the expression levels of the cancer stem-like cell markers CD44, OCT4, Nanog and ABCG2, as well as the EMT regulatory factor Slug were significantly enhanced in EpCAM-overexpressing cells and reduced in EpCAM-depleted HONE1 cells compared with control cells." (PMID 29305578, 2018). "For this reason, CD44 is critical for disseminated cancer cells to adapt to new environments." (PMID 30544868, 2018). "Moreover, high CD44 levels have been described as a characteristic feature of cancer stem-like cells in OSCC." (PMID 29669525, 2018). "For this purpose, we evaluated the expression of two cancer stem cell markers CD44 and ALDH1." (PMID 29306324, 2018). "•CD44 is related to migration, proliferation, and differentiation of cancer cells." (PMID 29872736, 2018). "The clinicopathological impacts of CD44s and its isoforms in promoting tumorigenesis suggest that CD44 may be a molecular target for cancer therapy." (PMID 29747682, 2018). "CD44 is thought to play a role in the adaptive plasticity of cancer cells." (PMID 29747682, 2018). "Thus, it appears that the Zeb1/CD44 loop evident in CGC is disrupted by stable Zeb1-independent repression of CD44 that is initiated as cancer cells are generated." (PMID 29930325, 2018). "The events leading to CD44 isoform molecular remodelling have direct implications in several cancer hallmarks and appear to vary according to the type of lesion, supporting the existence of disease-specific molecular fingerprints and potentially targetable biomarkers." (PMID 29983670, 2018). "CD44 is a membrane protein and is known as a stemness factor in cancer." (PMID 29356399, 2018). "Interestingly, GS signals in P were also significantly decreased, which suggests that interference with CD44 in cancer suppresses GS in both T and P." (PMID 29674746, 2018). "The role of CD44 has been examined in cancers such as leukemia, colon cancer, and breast cancer." (PMID 30372483, 2018). "However, because CD44 is expressed in almost all normal and cancer cells, specifically in normal prostate and PCa cells, there is a reported discrepancy and ambiguity regarding the functional aspects of this marker in prostate CSC maintenance." (PMID 30100995, 2018). "A correlation of MMP2/9 and CD44 expression was established in cancer cell line models suggesting that inhibiting the CD44-MMP axis might provide therapeutic targets for suppressing metastasis." (PMID 29747682, 2018). "CD44, one of the cancer stem cell markers, is activated as well." (PMID 30115078, 2018).
cancer (continued). "In order to distinguish CSCs from a larger number of cancer cells, there are different methods including utilization of markers in cells surface (such as CD44, CD 90 or CD133), side population (SP) assay as well as ALDEFLUOR assay related to ALDH1 enzyme activity." (PMID 30522488, 2018). "Thus, an important area of investigation is to further define the functional roles of CD44 isoforms in cancer and to determine the potential benefits of targeting these CD44 isoforms or their signaling pathways for cancer therapy." (PMID 29747682, 2018). "Not surprisingly, CD44 has been a hot topic in cancer research, frequently associated with more aggressive phenotypes and widely explored for cancer stem-cell identification." (PMID 29983670, 2018). "Moreover, the expression levels of cancer stemness markers (CD44 and CD133) and drug transporter MDR‐1 were significantly diminished in rats receiving combined therapy." (PMID 29683262, 2018). "CD133 and CD44 are widely considered as markers of cancer stem/progenitor-like cells." (PMID 29805745, 2018). "High levels of CD44 correlate with cancer progression and poor survival in melanoma patients." (PMID 30297743, 2018). "CD44 has been shown to promote resistance to apoptosis in some cancer cells." (PMID 29423071, 2018). "The functional role of CD44 in EMT has been studied in several cancers." (PMID 29747682, 2018). "Considering that CD44 has multifunctional roles and a promising prognostic value in various cancers, targeting CD44 for cancer therapy may prove to be a promising approach." (PMID 29872736, 2018). "Antibodies to CD44 are being studied in preclinical and clinical trials for cancer therapy." (PMID 29747682, 2018). "Much research has demonstrated the ability of HA to target CD44-overexpressing cancer cells." (PMID 30961058, 2018). "Cancer stem cell phenotype was assessed by the immunohistochemical analysis of CD44 and ALDH1." (PMID 29306324, 2018). "CD44 is a transmembrane protein known to be a cancer stem cell marker in HNSCC34." (PMID 30069008, 2018). "Apart from CD44, cancer stem cells displayed high levels of the OCT4 levels." (PMID 28240233, 2017). "In current study we found that RP-1, a specific peptide binding to CD44 protein, exhibited the potentials of specific binding to CD44 high-expressing cancer cells both in vitro and in vivo, and the capacity of predicting prognosis of human GC in a microarray assay." (PMID 28415792, 2017). "CD44, a potential progenitor cell marker, is normally expressed in undifferentiated cells near the base of cardia glands, and is also found in gastric dysplasia and cancer." (PMID 27448962, 2017). "Furthermore, CD44 is a marker for cancer stem cells and CD44 expressing cancer stem cells increases the likelihood of bone metastases through its interaction with HA." (PMID 28326306, 2017). "High CD44+ cell population remaining in live Sk-Hep-1 after anti-cancer reagent may explain the resistant response of HCC to conventional cancer therapy, which are contributed by CD44 expression." (PMID 29069721, 2017). "In addition, the expression of CD24 and CD44 was higher in malignant tumors compared to that in an inflamed pancreatic tissue." (PMID 28659655, 2017). "Indeed, here we are showing that the shift towards an epithelial phenotype by resminostat treatment correlates with downregulation of a cancer stem cell marker, CD44, and with a lower ability to form colonies (a functional assay of stemness capacity)." (PMID 29299154, 2017). "It included a number of genes with obvious cancer relevance including CD44, catenin b1 (CTNNB1), vimentin (VIM), cathepsins B and S (CTSB, CTSS), MMP9, XIAP, JunD, numerous proto-oncogenes (REL, YES, SET, FGR, CRK), and HSP90AA1 (which is a chaperone which stabilizes MIF as a client)." (PMID 28957348, 2017).